ALB (albumin)
Diseases named in the same sentence as ALB in open-access papers (continued):
Sharing a sentence is not in itself a finding about the gene and the disease.
Arthritis (continued). "Because albumin can bind drugs, it can impact how well they are distributed and how effective they are in treating arthritis." (PMID 40225279, 2025). "Remarkably, the injection of VHHmASC protein into mice also limited gout-associated monosodium urate (MSU) crystal driven pathology as well as arthritis induced by methylated bovine serum albumin (mBSA) and Freund’s adjuvant." (PMID 40785595, 2025). "Multivariable analysis on the associations between Neutrophil-percentage-to-albumin ratio and PHQ-9 score and all-cause mortality, CVD mortality among community-dwelling adults with arthritis aged 40 years or older." (PMID 40115342, 2025). "Multivariable analysis on the joint associations between Neutrophil-percentage-to-albumin ratio and PHQ-9 score and all-cause mortality and CVD mortality among community-dwelling adults with arthritis aged 40 years or older." (PMID 40115342, 2025). "Methylated bovine serum albumin (mBSA) antigen-induced arthritis (AIA) is another model, and it includes local immunization with a protein antigen (BSA, ovalbumin) followed by IA administration to the affected joints." (PMID 40493163, 2025). "According to joint involvement, the presence of arthritis was significantly associated with high CRP, low albumin, and high CAR (p < 0.05)." (PMID 39050391, 2024). "Antigen-induced arthritis (AIA) was established by intradermal injection of methylated bovine serum albumin in C57BL/6 mice, and one hour before the antigen challenge, either C-PC (2, 4, or 8 mg/kg) or PCB (0.1 or 1 mg/kg) were administered intraperitoneally." (PMID 37936684, 2023). "Local mono‐arthritis was induced with a systemic injection of methylated bovine serum albumin on the first day of loading, followed by a local injection in one knee 1 week later." (PMID 37457879, 2023). "The results showed that after adjusting for the covariates including age, gender, race, marital status, physical activity, DM, CVD, arthritis, CKD, and albumin, the TG/HDL-C ratio was negatively associated with the relative grip strength." (PMID 38026307, 2023). "Carvacrol albumin NPs were developed to encapsulate carvacrol where its immunomodulatory effect in the arthritis rat model was investigated." (PMID 35057036, 2022). "Both plant extracts showed significant reduction in albumin denaturation, dose-dependently, and was similar to that of NSAIDs having known anti-inflammatory potential against arthritis." (PMID 36234860, 2022). "Albumin-Methotrexate was more effective in the suppression of arthritis compared with methotrexate alone." (PMID 36365125, 2022). "To determine the role of B1R in an animal model of antigen-induced arthritis, we induced arthritis in mice using methylated bovine serum albumin (mBSA)." (PMID 35439173, 2022). "Up to our knowledge, our study is considered the first to formulate FLUR-loaded albumin NPs coated with HA to target the inflamed joints in arthritis." (PMID 35057036, 2022). "NPs based on HA and albumin are good drug delivery nanoplatforms for the management of arthritis owing to their stability, feasibility, and biocompatibility." (PMID 35057036, 2022). "JNK activation can also be detected in joints in a mouse model established by injection of methylated bovine serum albumin in complete Freund’s adjuvant at the base of the tail or in rats with adjuvant-induced arthritis (AIA)." (PMID 33198301, 2020). "In this study, we showed that continuous delivery of HSP65 in the gut mucosa by L. lactis is a potent tolerogenic stimulus inducing regulatory CD4+LAP+ T cells that prevented collagen-induced and methylated bovine serum albumin-induced arthritis in mice." (PMID 33072101, 2020). "To confirm our results, we also tested an acute model of arthritis induced by methylated bovine serum albumin (mBSA)." (PMID 33072101, 2020).
Arthritis (continued). "The ethanolic leaf extract and fractions were screened for anti-inflammatory properties using egg-albumin-induced paw edema, xylene-induced topical ear edema, formaldehyde-induced arthritis and ulcerogenic models." (PMID 31309077, 2019). "From the study, ethyl acetate and butanol fractions elicited better anti-inflammatory activities in egg-albumin-induced paw edema, formaldehyde-induced arthritis and xylene-induced topical ear edema." (PMID 31309077, 2019). "Methylated bovine serum albumin (mBSA)-induced arthritis in C57BL/6 mice belongs to antigen-induced arthritis." (PMID 29062314, 2017). "Arthritis was induced in New Zealand rabbits sensitized with methylated bovine serum albumin and subsequently intra-articularly injected with the antigen." (PMID 26872084, 2016). "This fact weakens substantially the role of the ascorbic acid concentration as an indicator of mild arthritis unless it is combined with another indicator as, for example, the albumin carbonyl groups (see next paragraph)." (PMID 26835218, 2016). "The present study was planned to evaluate the oxidative changes in the blood and specifically in the serum albumin of rats with adjuvant-induced mono- and poly-arthritis." (PMID 26835218, 2016). "Arthritis is induced by intraarticular injection of methylated bovine serum albumin (mBSA) in animals preimmunized with mBSA 2 and 3 weeks earlier." (PMID 24286140, 2013). "Antigen-induced arthritis was induced through intra-articular injection of methylated bovine serum albumin (mBSA) after two subcutaneous injections of mBSA and complete Freund's adjuvant." (PMID 22551402, 2012). "The STAT-1 decoy ODN was injected intra-articularly in methylated bovine serum albumin (mBSA)-immunized mice 4 h before arthritis induction." (PMID 16507120, 2006). "AIA is a Tcell-dependent experimental arthritis that is induced by intra-articular injection of antigen (methylated bovine serum albumin [mBSA]) into knee joints of preimmunized mice." (PMID 15743476, 2005). "Arthritis was induced by intra‐articular injection of methylated bovine serum albumin." (PMID 41006957, 2025). "We next adapted the so-call methylated bovine serum albumin (mBSA)/cytokine monoarticular arthritis model with exogenous IL-23 to determine whether we could develop an IL-23-driven arthritis model to explore putative downstream pathways." (PMID 39107827, 2024). "Moreover, IL-18 was found to be redundant in antigen-induced arthritis in response to an intra-articular injection of bovine serum albumin in mice immunized against this antigen." (PMID 37415987, 2023). "Human serum albumin (HSA) is employed as an agent to create a biomimetic nanoparticle system because proteins such as this have a tendency to concentrate in the synovial tissue of patients with arthritis." (PMID 37111636, 2023). "Additionally, albumin is a good candidate to be used as a targeting ligand in arthritis that can be selectively oriented to inflamed joints suffering from hypoalbuminemia." (PMID 35057036, 2022). "Albumin-based delivery of methotrexate was analyzed in a mouse model of arthritis." (PMID 36365125, 2022). "Orally administered AKBA exerts anti-arthritic activity in bovine serum albumin-induced arthritis." (PMID 34062884, 2021). "In a mouse model of methylated bovine serum albumin (mBSA)-induced arthritis, suppression of IL-33R (IL1RL1) expression in neutrophils could prevent IL-33-mediated neutrophil migration into the knee joint." (PMID 32719716, 2020). "Furthermore, acute oral pretreatment with doxycycline (3, 10, and 30 mg/kg) in an acute antigen (modified Bovine Serum Albumin)-induced arthritis model of the mouse dose-dependently inhibited mechanical hyperalgesia." (PMID 30949048, 2019). "Nog haploinsufficiency protected mice from arthritis induced by methylated bovine serum albumin." (PMID 31323019, 2019).
Arthritis (continued). "Arthritis (IA, n = 20) was induced in Lewis rats by intraarticular (ia) injection of 500 μg of methylated bovine serum albumin (mBSA) emulsified in complete Freund’s adjuvant (CFA) (10 μl) followed by an intraarticular booster of mBSA (50 μg) in saline (50 μl) administered at 7 and 14 days." (PMID 30059520, 2018). "Furthermore, an albumin fusion of the most crossreactive single-chain antibody prevents and reverses inflammation in the K/BxN mouse model of arthritis." (PMID 29654232, 2018). "In spite of the fact that the albumin concentration was decreased only in polyarthritis, its relative contribution to the total carbonyl groups was somewhat increased by both mono- and poly-arthritis (from 30 to 36 %)." (PMID 26835218, 2016). "Taking these hypotheses into consideration, the present work was planned to evaluate the oxidative status of both the serum and the albumin fraction of rats with adjuvant-induced arthritis with different degrees of severity." (PMID 26835218, 2016). "The results revealed that the levels of ascorbic acid in the serum and carbonyl groups in the albumin molecule can be regarded as indicators of the severity of arthritis since they were modified by both monoarthritis and polyarthritis, but to different degrees." (PMID 26835218, 2016). "To confirm this result, we established rabbit arthritis model with methylated bovine serum albumin." (PMID 25640174, 2015). "In the antigen induced arthritis model, disease induction involves stimulation of antibody production by the host, via administration of antigen (bovine serum albumin), while in CAIA model this initiation stage is bypassed by the administration of antibodies to collagen antibody type 2." (PMID 26347311, 2015). "DTH-arthritis was induced by eliciting a classical DTH reaction in one paw with methylated bovine serum albumin (mBSA), with the modification that a cocktail of type II collagen monoclonal antibodies was administered between the immunisation and challenge steps." (PMID 22676339, 2012). "Lower albumin levels in patients with more active arthritis may partly contribute to the lower pyridoxal 5'-phosphate level in these patients, although further study is needed for this postulation." (PMID 16277678, 2005). "Serum albumin is an acute-phase reactant that decreases during the flaring of active arthritis." (PMID 16277678, 2005). "Levels of serum albumin, serum nitrite/nitrate concentrations, hindpaw swelling, arthrogram scores, whole body bone mineral density (BMD), andbone erosions were evaluatedas markers of inflammation and destructive changes associated with arthritis." (PMID 15559373, 2004). "Thus, as ascorbic acid the serum albumin carbonyl groups may also be regarded as possible indicators of the severity of arthritis." (PMID 26835218, 2016). "The SHAP results reinforced this result, where arthritis exhibited the highest average SHAP value, followed by albumin, PT, oral ulcers, genital ulcers, and anti‐DNA." (PMID 41583997, 2026). "On the other hand, ILD, fever, arthralgia/arthritis, MMT, serum albumin levels, and anti-ARS antibody positivity were significantly lower in the Dysphagia group than in the Non-dysphagia group." (PMID 39429985, 2024). "Then, we included these variables in a stepwise regression analysis, and the results showed that age, gender, race, marital status, physical activity, DM, CVD, arthritis, CKD, and albumin were the final covariates." (PMID 38026307, 2023). "In the methylated bovine serum albumin (mBSA) induced arthritis mouse model, the contribution of RIPK2 to arthritis was highlighted by the reduction of neutrophil migration and mechanical hyper nociception in Ripk2−/− mice compared to the WT." (PMID 36959850, 2023). "The final prediction model included eight clinical variables (gender, fever, alopecia, periungual telangiectasia, digital ulcer, interstitial lung disease, arthritis/arthralgia, and Gottron sign) and four auxiliary results (WBC, CK, CKMB, and ALB)." (PMID 36703989, 2022).
Arthritis (continued). "In the present study in order to overcome this problem, we encapsulated carvacrol in the bovine serum albumin (BSA) nanoparticles and examined its therapeutic and immunomodulatory effects in adjuvant-induced arthritis (AIA)." (PMID 32922489, 2020). "Arthritis induction increased the activity of plasma MPO (+400%) and globulins (+30%) while it decreased the levels of albumin (−44%) and the albumin/globulin ratio (−60%)." (PMID 30210649, 2018). "Moreover, we could demonstrate an intensive accumulation of albumin in the paws affected arthritis." (PMID 23006786, 2012). "The arthritis and vasculopathy features highlights the systemic (albeit subtle) nature of the inflammation with possible impact at the BBB (given that 1/3 have elevated protein and/or albumin quotient)." (PMID 39224487, 2024). "Interestingly, IVIG treatment or ant-murine albumin antibodies protected mice against KBN serum induced arthritis, suggesting the importance of antibody-FcR interactions in arthritis pathogenesis." (PMID 29495570, 2018). "Experimental methylated bovine serum albumin induced arthritis was not significantly attenuated by FL treatment, whereas treatment with sumatinib (a tyrosine kinase receptor inhibitor directed against the FLT3 receptor) protected mice from joint damage." (PMID 25849330, 2015). "Thus, immune responses to citrullinated rat serum albumin (Cit-RSA) and to unmodified rat serum albumin (RSA) were examined as well as arthritis development induced by immunisation with citrullinated rat collagen type II (Cit-CII) or unmodified CII." (PMID 15899032, 2005). "Patients with OA and RA exhibited higher neutrophil percentages, lower albumin levels, and markedly elevated NPAR compared to individuals without arthritis." (PMID 39917306, 2025).
preeclampsia (91 papers, 2012 to 2026). Preeclampsia is a hypertensive disorder of pregnancy that is characterized by new-onset hypertension with proteinuria presenting after 20 weeks of gestation, and depending on mild or severe forms may initially present with severe headache, visual disturbances, and hyperreflexia. "Multivariate regression analysis revealed that nulliparity, advanced maternal age, high body mass index, and low serum albumin levels were independently associated with preeclampsia." (PMID 41594281, 2026). "Our recent meta-analysis based on nine clinical studies identified the three most reliable oxidative stress-related diagnostic biomarkers for preeclampsia including Ischemia-Modified Albumin (IMA), UA, and MDA." (PMID 40109359, 2025). "Albumin is a scavenger of free radicals, and reactive oxygen species has been implicated in the pathogenesis of preeclampsia." (PMID 39857389, 2025). "Understanding the antioxidant properties of albumin opens new avenues for therapeutic intervention and sheds light on novel strategies for combating preeclampsia associated with oxidative damage." (PMID 39857389, 2025). "Results of multivariate logistic regression conducted to evaluate the relationship between the fibrinogen-to-albumin ratio and risk of preeclampsia." (PMID 41246030, 2025). "One of the hallmark signs of preeclampsia is proteinuria, where significant amounts of protein, including albumin, are lost in the urine due to glomerular endothelial injury." (PMID 39408980, 2024). "In the scenario of inflammation and proteinuria associated with preeclampsia, serum albumin is expected to decrease, whereas sPD-L1 increases as a protective effect." (PMID 39328700, 2024). "They reported that albumin levels less than 3 g/dL were commonly associated with the severity of preeclampsia and poor perinatal prognosis." (PMID 36140589, 2022). "Preeclampsia is a sub-unit of gestational hypertension and, by the current European guidelines, is associated with significant proteinuria (> 0.3 g/24 h or albumin to creatinine ratio ≥30 mg/mmol)." (PMID 36082119, 2022). "Marked by high blood pressure (BP) and the presence of albumin in urine, preeclampsia is a risk factor for the potential development of severe preeclampsia or full-blown eclampsia and should be monitored." (PMID 31527058, 2019). "Given the central role of inflammation and vascular dysfunction in the development of preeclampsia, this study aimed to evaluate the relationship between the fibrinogen-to-albumin ratio (FAR) multiplied by 100 (FAR × 100) and risk of preeclampsia in this high-risk group." (PMID 41246030, 2025). "In total, an exposure to TiO2 NPs during pregnancy might increase the risk of human preeclampsia through increased maternal arterial pressure and urinary albumin levels, as well as causing fetal growth restriction in the offspring." (PMID 38787146, 2024). "Proteinuria in preeclampsia is caused by glomerular alterations like endothelial cell enlargement and fenestrae disruption, resulting in increased protein permeability, which includes high-molecular-weight proteins like albumin." (PMID 35464597, 2022). "Preeclampsia is associated with increased capillary permeability resulting in endothelial damage which is also responsible for the observed proteinuria and low level of the serum total protein and albumin." (PMID 28133548, 2017). "However, other research supports the idea that alterations in serum albumin, as part of oxidative stress responses, could contribute to the pathophysiology of preeclampsia and may hold diagnostic value when combined with other biomarkers." (PMID 40648529, 2025). "Conversely, platelet (PLT) and albumin levels were significantly higher in the control group than in the preeclampsia group." (PMID 41594281, 2026). "In multivariate regression model, gestational age (GA), body mass index (BMI), UA, ALB, LDH and MPV were found to be independent factors associated with gestational hypertension and preeclampsia." (PMID 41706753, 2026).